PSAT1 (phosphoserine aminotransferase 1)
Diseases named in the same sentence as PSAT1 in open-access papers (continued):
Sharing a sentence is not in itself a finding about the gene and the disease.
ovarian carcinoma (11 papers, 2020 to 2025). A malignant neoplasm originating from the surface ovarian epithelium. "In this work, we used computational approaches to find putative Traditional Chinese Medicine (TCM) inhibitors that target Phosphoserine Aminotransferase 1 (PSAT1), a crucial enzyme linked to the development of early-stage ovarian cancer." (PMID 39913473, 2025). "Traditional Chinese medicine (TCM) offers a fascinating route for investigating possible inhibitors targeting Phosphoserine Aminotransferase 1 (PSAT1) in early-stage ovarian cancer." (PMID 39913473, 2025). "Traditional Chinese medicine, with its holistic approach and abundant natural substances, is explored for its potential to inhibit PSAT1 in early-stage ovarian cancer." (PMID 39913473, 2025). "Recent studies identified PSAT1 as a viable therapeutic biomarker in the early stages of ovarian cancer." (PMID 39913473, 2025). "PSAT1 is essential for the serine biosynthesis pathway, which supports the growth and survival of cancer cells, especially those in the early stages of ovarian cancer." (PMID 39913473, 2025). "Overexpression of PSAT1 in human U937 cells significantly promotes cell proliferation, whereas knockdown of PSAT1 markedly inhibits the clonogenicity and cell cycle of ovarian cancer cells and promotes their apoptosis." (PMID 40867682, 2025). "Phosphoserine aminotransferase (PSAT1) is a serine catalase that plays an important role in the development of ovarian cancer." (PMID 35719392, 2022). "MicroRNA-195-5p reduces angiogenesis and cisplatin resistance of ovarian cancer by restraining the PSAT1-mediated GSK3β/β-catenin pathway." (PMID 33526036, 2021). "In the ranking list of positive co-expression genes, the fifth gene PSAT1 was closely related to platinum resistance in ovarian cancer PSAT1 downregulation reduced the resistance and enhanced the sensitivity of ovarian cancer cells to cisplatin." (PMID 33585454, 2020). "In ovarian cancer, overexpression of miR-195-5p can reduce cisplatin resistance and angiogenesis via PSAT1-depedent GSK3β/β-catenin signaling pathway." (PMID 32201531, 2020). "Elevated levels of PSAT1 in the tumor tissues is correlated with the prognosis of ovarian cancer." (PMID 33526036, 2021). "By providing light on possible TCM-based inhibitors targeting PSAT1, this publication seeks to further the knowledge in the area and open the door for additional preclinical and clinical research in the search for better treatment approaches for early-stage ovarian cancer." (PMID 39913473, 2025). "Studies have shown that PSAT1 is involved in regulating cell proliferation in vitro; overexpression of PSAT1 in human U937 cells significantly promotes cell proliferation, while knockdown of PSAT1 significantly inhibits the cell cycle and promotes apoptosis in ovarian cancer cells." (PMID 40867682, 2025). "DO analysis revealed that DEGs PSAT1, FOLR1, ABCB1, SFRP1, SFRP1, BUB1B have a greater association with female reproductive system tumor-related diseases, such as malignant ovarian surface epithelial-mesenchymal tumor, ovarian epithelial carcinoma, and ovarian cancer." (PMID 35719392, 2022). "The study aims to find a novel approach to early-stage ovarian cancer treatment using computational identification and validation of possible TCM inhibitors targeting PSAT1." (PMID 39913473, 2025). "In ovarian cancer, a function of LPP and PSAT1 was discovered in endothelial cell motility through focal adhesion and stress fibre production, as well as in cell proliferation and metastasis." (PMID 39309198, 2024). "The computational studies support the hypothesis that Coniferin and Tetrahydrocurcumin can be potent inhibitors of PSAT1 in early-stage ovarian cancer, and both are natural compounds, relatively non-toxic, making them good candidates for further development as PSAT1 inhibitors." (PMID 39913473, 2025).
lung adenocarcinoma (10 papers, 2019 to 2025). A carcinoma that arises from the lung and is characterized by the presence of malignant glandular epithelial cells. "Nf1 suppression increases Kras-driven lung adenocarcinoma and affects PSAT1-related glutamate dependency." (PMID 33526036, 2021). "Similarly, another study showed that overexpression of PSAT1 promotes the metastasis of lung adenocarcinoma via the inhibition of STAT1 as well as its downstream targets, IRF1 and IFNG." (PMID 40298450, 2025). "For example, in lung adenocarcinoma, overexpression of PSAT1 may lead to tumor metastasis and erlotinib resistance." (PMID 36998464, 2023). "Recent work shows that in lung adenocarcinoma, PSAT1 overexpression could contribute to erlotinib resistance and tumor metastasis." (PMID 36998464, 2023). "Additionally, we found increased protein expression of ATF4 and PHGDH, along with upregulated mRNA levels of PCK2, PHGDH, PSAT1, and PSPH, in DNM1L‐KO lung adenocarcinoma cell lines." (PMID 33152171, 2021).
breast tumors (8 papers, 2017 to 2025). "We find that the serine synthesis pathway gene PSAT1 is the most depleted metabolic gene in luminal breast tumors relative to basal tumors." (PMID 35045283, 2022). "Interestingly, luminal breast tumors have the highest PSAT1 methylation and are the only tumor type to show consistently high PSAT1 methylation, although outliers can be found in most tumor types." (PMID 35045283, 2022). "Accordingly, luminal breast tumors have the lowest PSAT1 mRNA expression of any tumor type, suggesting that low PSAT1-induced sensitivity to S/G starvation may be a luminal breast tumor-specific vulnerability." (PMID 35045283, 2022). "Importantly, we found a significant correlation of PSAT1 expression with IKKε levels and the inflammatory grade of the same samples, indicating association between inflammation and SBP in breast tumours." (PMID 31930708, 2020). "Interestingly, among the top dysregulated hits, a set of genes (DEDD, ABCB10, UAP1, KCNJ9, and PSAT1) are located close together on chromosome 1q23.3–42.1 and are co-amplified in >15% of breast tumors from 164 cancer genome studies." (PMID 31253784, 2019). "Interestingly, hypermethylation of the PSAT1 gene in luminal breast tumors is reminiscent of T cell acute lymphoblastic leukemia (T-ALL), in which hypermethylation of the asparagine synthetase gene sensitizes T-ALL cells to degradation of plasma asparagine with l-asparaginase." (PMID 35045283, 2022). "Moreover, we have identified a subset of basal, estrogen receptor negative (ER−) highly proliferative breast tumours where IKKε and PSAT1 are both overexpressed, confirming the pathophysiological role of our findings." (PMID 32783398, 2020). "Finally, we show that in a highly proliferative set of ER negative, basal breast tumours, IKKε and PSAT1 are both overexpressed, corroborating the link between IKKε and the SBP in the clinical context." (PMID 32783398, 2020). "Analysis of the proteome of human breast tumors also revealed very low levels of PHGDH and PSAT1 (but not PSPH) protein in luminal breast tumors." (PMID 35045283, 2022).
esophageal cancer (8 papers, 2018 to 2024). A primary or metastatic malignant neoplasm involving the esophagus. "In previous studies, PSAT1 was shown to be associated with the development and metastasis of a variety of cancers, including lung, liver, ovarian, colorectal, and esophageal cancer." (PMID 39199378, 2024). "Yan proved that downregulating PSAT1 expression significantly inhibited the growth of esophageal cancer cells." (PMID 36732787, 2023).
liver cancer (8 papers, 2021 to 2025). An epithelial or non-epithelial malignant neoplasm that arises from the liver. "Notably, pharmacological targeting the PSAT1-p5372P interaction by aminooxyacetic acid (AOA) crippled the growth of liver cancer cells carrying the p5372P variant in both in vitro and patient-derived xenograft models." (PMID 36788227, 2023). "TRIM71 activates the glycine/serine metabolism pathway by remodeling the transcription of PSPH and PSAT1, thereby controlling the oncofetal characteristics of liver cancer and tumor initiation and progression." (PMID 39267787, 2024). "TRIM71 forms a protein complex with IGF2BP1, enhances mRNA stability of CEBPA with m6A-dependent manner, remodels PSPH and PSAT1 transcription, strengthens serine/glycine metabolism, and ultimately promotes liver cancer progression." (PMID 39267787, 2024). "TRIM71 binds to and stabilizes the mRNAs of CEBPA, remodels PSPH and PSAT1 transcription, enhances the serine/glycine metabolic pathway, and ultimately promotes liver cancer progression." (PMID 39267787, 2024). "The mRNA or protein expression of PSAT1 was positively associated with TFAM in CCLE liver cancer cell lines and liver cancer patient tissues." (PMID 36788227, 2023). "To ascertain the role of PSAT1 in liver cancer progression, tissue samples and datasets were analyzed and we found that the protein or mRNA levels of PSAT1 were negatively correlated with the overall survival rate of HCC patients." (PMID 36788227, 2023). "The interaction between PSAT1 and p5372P is critical for maintaining the metastatic potential of liver cancer cells through preserving mitochondrial activity." (PMID 36788227, 2023). "Importantly, we found that expression of PSAT1 was elevated in lung metastases compared with primary liver cancer." (PMID 36788227, 2023). "Importantly, it forms a protein complex with IGF2BP1, which binds to and stabilizes CEBPA mRNA levels through an m6A-dependent manner, enhancing CEBPA mediated PSPH/PSAT1 transcription and remodeling serine/glycine metabolism, and ultimately accelerates liver cancer growth and tumorigenicity." (PMID 39267787, 2024). "Moreover, PSAT1 knockout or knockdown significantly impaired the migration of liver cancer cells (PLC/PRF/5) and CRC cells (HT29) expressing p5372P variants, while overexpression of PSAT1 promoted the migration and invasion of HepG2 cells containing p5372P variants." (PMID 36788227, 2023). "Consistent with our recent findings in pediatric liver cancer, we also observed that CM272 markedly reduced the expression of amino acid metabolic enzymes (ASNS, PYCR1, BCAT2), as well as genes involved in the serine pathway (PHGDH, PSPH, PSAT1)." (PMID 39810240, 2025). "Importantly, ATRA or A-485 decreased mRNA levels of TRIM71, CEBPA, PSPH, PSAT1 and protein levels of TRIM71 and CEBPA, suggesting the transcriptional regulation of RXRA and EP300 to TRIM71 in liver cancer." (PMID 39267787, 2024). "Conversely, PSPH and PSAT1 mRNA levels and protein levels were dramatically upregulated in TRIM71 and YAP5SA + TRIM71 mice liver tumor tissues compared to the control group, and inhibition of TRIM71 or CEBPA decreased cellular serine and glycine levels in HuH-7 and Hep3B liver cancer cells." (PMID 39267787, 2024). "Moreover, PSAT1 and TFAM were enriched in the invasive front of liver cancer tissues." (PMID 36788227, 2023).
melanoma (8 papers, 2013 to 2025). A malignant, usually aggressive tumor composed of atypical, neoplastic melanocytes. "The gene PSAT1, together with ATF4 and NRF2, is associated with thiol starvation in melanoma." (PMID 38785552, 2024). "PSAT1 is a critical component of BRAF inhibitor resistance of pancreatic cancer, melanoma, and NSCLC." (PMID 33526036, 2021). "Key enzymes such as D-3-Phosphoglycerate dehydrogenase (PHGDH), phosphoserine aminotransferase 1 (PSAT1), and phosphoserine phosphatase (PSPH) are upregulated in melanoma, enhancing nucleotide synthesis, methylation reactions, and antioxidant defense via glutathione production." (PMID 40573249, 2025). "The serine biosynthesis pathway, which involves the enzymes phosphoglycerate dehydrogenase (PHGDH), phosphoserine aminotransferase 1 (PSAT1), and phosphoserine phosphatase (PSPH), is frequently upregulated in malignancies such as triple-negative breast cancer and melanoma." (PMID 40535116, 2025). "Similarly, in the PRJEB23709 melanoma anti-PD1 immunotherapy cohort, the levels of PSAT1, PSPH, and SHMT1/2 were significantly reduced in PR or CR patients treated with anti-PD1 compared with drug-resistant PD patients." (PMID 37223471, 2023). "Many of these genes, including Phgdh, Psat1, and Psph, play important roles in serine biosynthesis, a process that has been shown to accelerate melanoma progression and confer resistance of BRAF V600E mutant melanoma to the targeted inhibitor vemurafenib." (PMID 32175283, 2020). "In addition, PSAT1 activation by PERK could promote macrophage immunosuppressive activity through serine biosynthesis and regulate the efficacy of immunotherapy in melanoma." (PMID 36110969, 2022).
hepatocellular carcinoma (7 papers, 2020 to 2025). A malignant tumor that arises from hepatocytes. "Key cancer-related pathways such as “Gastric cancer”, “Hepatocellular carcinoma” and “Proteoglycans in cancer” were prominently identified in network, bar and bubble plots, and genes such as NME1, PSAT1, AHCY and PIGR were significantly involved." (PMID 40567612, 2025). "C-MYC directly controls the transcription of PHGDH, PSAT1, PSPH, SHMT1, and SHMT2 in human hepatoma and HeLa cells." (PMID 37949226, 2023). "To determine the association of the PPP and SGS pathways in clinical HCC, we analysed PHGDH, PSAT1 and G6PD RNA expression in HCC tumour and non-tumour liver tissue from the Cancer Genome Atlas (TCGA) liver hepatocellular carcinoma (LIHC) database." (PMID 33028928, 2020).
glioblastoma (6 papers, 2018 to 2025). The most malignant astrocytic tumor (WHO grade IV). "In the SSP, SHMT2 and PSPH are upregulated but the upstream enzyme PSAT1 is downregulated in glioblastoma." (PMID 36175487, 2022). "Our results showed that SHMT2 and PSPH were upregulated in SSP, while their upstream enzymes PSAT1 or PHGDH were downregulated or unaffected in glioblastoma, suggesting that the SSP in glioblastoma might be independent of carbon flux from glycolysis." (PMID 36175487, 2022). "Regorafenib provokes mortal autophagy of glioblastoma by maintaining PSAT1." (PMID 33526036, 2021). "Interestingly, although the methylation status of PSAT1 is not different between glioblastoma and normal tissues, hypermethylation of PSAT1 was associated with shorter survival duration of glioma." (PMID 36105075, 2022). "SHMT2 and PSPH were upregulated and the upstream enzyme PSAT1 was downregulated, suggesting that SHMT2 and PSPH play key roles in activation of the SSP in glioblastoma." (PMID 36175487, 2022).
glioma (6 papers, 2019 to 2023). A benign or malignant brain and spinal cord tumor that arises from glial cells (astrocytes, oligodendrocytes, ependymal cells). "When LGG patients in the CGGA dataset were classified into 4 groups according to the WHO grade and IDH1 mutation status, the expression levels of PSAT1 were highest in the group of grade II gliomas with IDH1 mutations, which was supposed to be the group with the best prognosis in LGGs." (PMID 31861486, 2019). "Another positive prognostic gene in gliomas recently identified is phosphoserine aminotransferase 1 (PSAT1)." (PMID 36425564, 2022). "Datasets from The Cancer Genome Atlas (TCGA) and the Chinese Glioma Genome Atlas (CGGA) were further used to explore the prognostic role of PSAT1 gene." (PMID 31861486, 2019). "The prognostic significance of PSAT1 in LGGs was further validated using Chinese Glioma Genome Atlas (CGGA) dataset and the REMBRANDT (Repository for Molecular Brain Neoplasia Data) cohort." (PMID 31861486, 2019). "This indicates that PSAT1 may play a completely different role in glioma compared to other tumors, which also reflects the heterogeneity of tumor occurrence and development and the particularity of the brain tumor microenvironment." (PMID 36105075, 2022). "In our results, the expression levels of PSAT1 were also significantly higher in grade II and III gliomas with IDH1 mutations than in those of IDH1 wild-type, and significantly higher in grade II gliomas than in grade III gliomas." (PMID 31861486, 2019). "From literature review and our analyses, we conclude that the prognostic role of PSAT1 overexpression in gliomas, including LGGs and GBM, might be different from that in other cancer types." (PMID 31861486, 2019). "Similarly, the expression levels of PSAT1 were also shown to be significantly higher in grade II gliomas than in grade III gliomas." (PMID 31861486, 2019). "The results showed that PSAT1 was highly expressed in gliomas, including LGGs and GBMs." (PMID 31861486, 2019). "The results of immunohistochemical (IHC) staining showed that PHGDH, PSAT1, and PSPH expression levels in both low-grade gliomas and high-grade gliomas (GBM) are much higher than those in normal human brain tissue." (PMID 38098117, 2023). "It is interesting to note that, as in glioma, LGG showed a clear positive correlation between PSAT1 expression and infiltration of B cells, CD8+ T cells and neutrophils, but a negatively correlation with infiltration of CD4+ T cells." (PMID 36105075, 2022). "In addition, analyses of The Gene Expression Omnibus (GEO) database (GSE4290; n = 180) showed that PSAT1 and PSPH genes are upregulated in human gliomas tissues, compared to normal tissues." (PMID 38098117, 2023).
triple-negative breast carcinoma (6 papers, 2019 to 2025). An invasive breast carcinoma which is negative for expression of estrogen receptor (ER), progesterone receptor (PR), and human epidermal growth factor receptor 2 (HER2). "Similarly, the selective loss of PSAT1 also abrogates migration, invasion, and metastasis in triple-negative breast cancer, suggesting that PSAT1 induces the migratory potential for metastasis without synthesizing serine." (PMID 36582785, 2022). "A particular defect of PSAT1 represses experimental metastasis, invasion, and migration in triple-negative breast cancer." (PMID 33526036, 2021). "Results showed that RIT1 expression was higher (p<0.05) in triple negative breast cancer and high grade ovarian cell lines than in the other cell lines; PSAT1 expression is significantly higher in triple negative breast cancer cell lines (p<0.001) as compared to the other breast cell lines." (PMID 31105872, 2019).
leukemia (5 papers, 2016 to 2025). A malignant (clonal) hematologic disorder, involving hematopoietic stem cells and characterized by the presence of primitive or atypical myeloid or lymphoid cells in the bone marrow and the blood. "While PSAT1 silencing may be a pre-existing state of the leukemia cell-of-origin, it may also be a more direct downstream consequence of the genetic drivers associated with SA AML." (PMID 40462988, 2025). "However, it has not been previously studied in leukemia, and we found that a −SG diet extended the survival of mice engrafted with four different auxotrophic, PSAT1-suppressed AML cell lines, as well as MOLM13 AML cells made auxotrophic through PSAT1 knockout." (PMID 40462988, 2025). "These leukemias consistently suppressed the SSP enzyme PSAT1, failed to synthesize serine, responded to SG restriction in vivo, and were rescued by restoring PSAT1." (PMID 40462988, 2025).
nasopharyngeal carcinoma (5 papers, 2018 to 2023). A carcinoma arising from the nasopharyngeal epithelium. "Interestingly, high PSAT1 expression were associated with poor outcome in nasopharyngeal carcinoma." (PMID 30405052, 2018). "PSAT1 serves as a biomarker of worse prognosis of nasopharyngeal carcinoma." (PMID 33526036, 2021).